BRCA2 (BRCA2 DNA repair associated)
Diseases named in the same sentence as BRCA2 in open-access papers (continued):
Sharing a sentence is not in itself a finding about the gene and the disease.
cancer (continued). "Of interest, micronuclei were also observed in cancer cells in which FANCD1 (BRCA2) expression was abrogated." (PMID 35198459, 2022). "Based on the estimated overall risk for breast cancer protein-truncating variants, ATM, BRCA1, BRCA2, CHEK2 and PALB2 were identified as the major cancer susceptibility genes in the study population." (PMID 36568162, 2022). "In 1998, Myriad Genetics was awarded a patent for both BRCA1 and BRCA2 genes and began offering commercial testing for these hereditary forms of cancer." (PMID 35626055, 2022). "While BRCA1 and BRCA2 are the most well-studied genes, inclusion of other HCS genes will improve cancer risk prediction." (PMID 35877228, 2022). "BRCA1 and BRCA2 are tumor suppressor genes with a key role in DNA repair processes and cell-cycle checkpoints, in response to DNA damage, whose mutations may induce genomic instability, cell-cycle dysregulation, and accumulation of other mutations, thus increasing the risk of cancer development." (PMID 36359251, 2022). "We also found recurrent CRISPR-induced indels from both NRASG12V and KRASG12D screens in genes whose loss has been linked to ICC but that have not previously been shown to genetically interact with mutant RAS in this cancer including Brca2, Nf2, and Plk2." (PMID 35074757, 2022). "The study results suggest that the range of cancer types associated with pathogenic variants in BRCA1 and BRCA2 is broader than that determined from previous analyses, potentially indicating the broader clinical relevance of BRCA1/2 genetic testing." (PMID 35420638, 2022). "Among these, six cancers had additional genetic alterations: BRAF fusions (n = 2), and one each with RET fusion plus BRCA2 loss of function mutation, IDH1 mutation, RAF1 fusion, and EML4-NTRK3 fusion." (PMID 36124727, 2022). "For example, the rare missense BRCA2 c.9004G > A; p.Glu3002Lys reported in a number of unrelated cancer families from the North American population was initially classified as a variant of uncertain clinical significance in the BIC database." (PMID 34298626, 2021). "Germline mutations mainly in the BRCA2 gene lead to an increased risk of breast cancer, as well as a higher risk of developing PDAC, with a 2–6-fold increase in cancer risk compared with the general population." (PMID 34359820, 2021). "Compared to other models, this tool allows the incorporation of genotypes related to other cancer susceptibility genes which include BRCA1 and BRCA2, as well as family history, reproductive risk factors and ductal atypical hyperplasia." (PMID 34771713, 2021). "Other examples include cancer susceptibility genes such as BRCA1 and BRCA2 that occur more commonly in Ashkenazi Jewish populations." (PMID 33842350, 2021). "We confirmed a higher earliness frequency of cancer onset with BRCA1 than BRCA2 for the youngest age groups as well." (PMID 34356116, 2021). "Two subnetworks in TCGA-LUAD, KRAS-SHC3 and BRCA2-FANCA, have been shown to have mutually exclusive mutations and more than half of those genes are present in COSMIC cancer census genes." (PMID 34906079, 2021). "A single unrepaired DSB in a cell can be cytotoxic, additionally mutations or down-regulation of DNA repair proteins, associated with the repair of DSBs, are strongly linked with inherited cancer risk (BRCA1, BRCA2, ATM)." (PMID 33669398, 2021).
cancer (continued). "It is worth noting that our results of olaparib resistance in different BRCA1 mutant cells due to EMI1 downregulation that were associated with high RAD51 levels are in line with previous results done either in BRCA1 mutant cancer cells or BRCA2 mutant ones." (PMID 33412559, 2021). "Our findings are similar to two other studies investigating the cancer spectrum of male BRCA1/2-mutation carriers, where a higher number of overall cancers as well as BC were observed in patients with a BRCA2-mutation." (PMID 34575694, 2021). "How does one decide which functional assay is critical for the long-term effects of BRCA2 haploinsufficiency leading to the eventual outgrowth of a clinically diagnosable cancer?" (PMID 34065235, 2021). "As somatic events in BRCA1 or BRCA2, genomic reversion is known as a mechanism for acquiring resistance to PARPi or platinum chemotherapy in cancer cells." (PMID 35008774, 2021). "In 5.8% of survivors, pathogenic or likely pathogenic variants were detected in specific cancer predisposition genes, e.g., Rb1, NF1, BRCA2." (PMID 34680213, 2021). "Some authors have tried to set up different methods for VUS classification for the BRCA1, BRCA2, and the PALB2 genes in order to predict variant pathogenicity and the resulting susceptibility to cancer." (PMID 34206535, 2021). "But the most remarkable pro-cancer RAD52 phenotype is seen in cancer cells deficient in any of the following DNA repair proteins: BRCA1, BRCA2, PALB2, XAB2 or RAD51 paralogs: RAD51B, RAD51C, RAD51D, XRCC2 and XRCC3." (PMID 34887904, 2021). "The activity of PARP inhibitors in patients with BRCA1 or BRCA2 mutant cancers was the first clinical demonstration of synthetic lethality for cancer therapy." (PMID 33578789, 2021). "In these cancer types, after PARPi administration, patients carrying specific mutations in the breast cancer 1 (BRCA1) and 2 (BRCA2) suppressor genes have shown better response when compared to wild-type carriers." (PMID 34439854, 2021). "For example, BRCA1 and BRCA2 are mostly specific to a small set of cancer types such as breast and ovarian cancer, and are highly enriched in Ashkenazi Jews2." (PMID 34290314, 2021). "Although PARP inhibitors were found to be selectively active in a subset of tumors harboring BRCA1 or BRCA2 mutations due to the synthetic lethality of PARP inhibition and this particular HRD, it also has a role in BRCA wild type cancers." (PMID 34201502, 2021). "Our data thus far indicated that GSK3 inhibition strongly synergized with PARPi in BRCA2-deficient and BRCA1/2-proficient cancer cells in vitro." (PMID 33589588, 2021). "Collectively, our work uncovers PP2A-B56 as a positive regulator of BRCA2 function in HR with clinical implications for BRCA2 and PP2A-B56 mutated cancers." (PMID 34593815, 2021). "Topoisomerase 1 inhibitors have been shown to be effective in cancer therapy of HR-deficient, Schlafen 11-positive cells in association with Olaparib, for the treatment of BRCA1-, BRCA2-, and PALB2-deficient cells." (PMID 34639169, 2021). "We were curious to see if RPA:RAD52 PPI inhibitors would show synthetic lethality in HR-deficient cancer cell lines, so we examined the cytotoxicity of quinacrine, mitoxantrone, and doxorubicin in cells with impaired BRCA1 or BRCA2 function." (PMID 33784323, 2021). "RESULTS: Of the 323 men included, 45 (13.9%) had a primary cancer diagnosis, many of whom were BRCA2 carriers (75.5%)." (PMID 34575694, 2021). "This literature review addresses cancer predisposition genes, including BRCA1, BRCA2, and PALB2; synthetic lethality in the context of DNA repair machinery; and historical and current treatment options for breast and ovarian malignancies with these mutations." (PMID 34070674, 2021). "Our results demonstrate that β-catenin activation acts synergistically with BRCA1 or BRCA2 abrogation to kill cancer cells." (PMID 34389725, 2021).
cancer (continued). "This literature review addresses cancer predisposition genes, including BRCA1, BRCA2, and PALB2, synthetic lethality in the context of DNA repair machinery, as well as available treatment options." (PMID 34070674, 2021). "Given the unique genetic architecture of the FC population of Quebec, it is likely that carriers of FANCI c.1813C>T have common ancestors as has been shown with carriers of frequently occurring pathogenic variants in BRCA1, BRCA2, and MSH6 in cancer families." (PMID 34861889, 2021). "PARPi selectively induce synthetic lethality in cancer cells with homologous recombination deficiencies (HRDs), the most notable being cancer cells harboring mutations in the BRCA1 and BRCA2 genes." (PMID 33487630, 2021). "In other cancers, signature 3 mutations often accompany biallelic inactivation of BRCA1 or BRCA2, where the inability to repair DNA predicts good responses to platinum therapy." (PMID 34580349, 2021). "In 2009, Fong et al20 published their results of the first PARPi trial that was enriched for patients with cancer who had BRCA1 and BRCA2 mutations." (PMID 34712892, 2021). "Cancer cells with defective BRCA1 or BRCA2 tumor suppressor genes cannot perform homologous recombination." (PMID 34070839, 2021). "In particular, HT inhibits homologous recombination, induces BRCA2 degradation, sensitizes cancer cells to poly(ADP-ribose) polymerase-1 inhibition, and affects DNA-PKCs." (PMID 34201993, 2021). "For both groups, P/LP variants were identified in genes that are associated with heritable CRC and in genes associated with other known cancer syndromes, such as BRCA1 and BRCA2 in HBOC." (PMID 34585040, 2021). "Future studies should attempt to identify variants that influence gene expression and post-transcription modifications to improve our understanding of BRCA1 and BRCA2, as well as their related cancers." (PMID 35087763, 2021). "Germline and somatic mutations across (i.e., MMR versus HR) and within (i.e., BRCA1 versus BRCA2) DDR pathways showed variable associations with TMB, neoantigen loads, and indel neoantigen hotspots in a cancer-dependent manner." (PMID 34095878, 2021). "Seven kinds of RAD52i have been proposed, and some of these compounds are approved by the FDA, indicating that RAD52i is an attractive approach for BRCA1-, BRCA2-, RAD51 paralog-, and PALB2-deficient cancer." (PMID 33922657, 2021). "Here, we performed a comprehensive analysis for BRCA1/2 variants and associated cancer risk in Korean patients with respect to VUS and PLPVs in BRCA1 and BRCA2." (PMID 34063308, 2021). "Relative to BRCA1 and BRCA2, less is known of the role of BRIP1 and CHEK2 cancer predisposing genes in conferring risk of BC and OC in FCs." (PMID 34298626, 2021). "New cancer-predisposing gene (CPG) candidates have been investigated with a focus on members of the Fanconi anaemia (FA) DNA repair pathway involving BRCA1 and BRCA2 function." (PMID 34861889, 2021). "The end goal of functional analysis is to derive a highly sensitive, specific, and predictive score that can be integrated with prior methods to correctly classify the large number of BRCA2 VUS and unmask both cancer risk and response to chemotherapeutics." (PMID 34065235, 2021). "In cancers that contain loss-of-function mutations in BRCA1 and BRCA2, back-up DNA repair pathways exist." (PMID 34950659, 2021). "The best-known examples of cancer predisposition genes are the tumor suppressors BRCA1 and BRCA2 involved in breast and ovarian cancers." (PMID 34290314, 2021). "Boadicea v4 Beta (Centre for Cancer Genetic Epidemiology, 2020) considers BRCA1, BRCA2, PALB2, CHEK2, and ATM mutations in the same cancers." (PMID 34406119, 2021). "Due to elevated cancer risk, RRBSO is recommended at the age of about 35–40 years in BRCA1 and 40–45 years in BRCA2 mutation carriers, whereby family planning and the earliest age at diagnosis in affected family members have to be taken into consideration." (PMID 33885953, 2021).
cancer (continued). "Given the observed hypersensitivity of a broad range of BRCA2-defective cancer cells to NSC617145, we tested the in vivo response of BRCA2-deficient tumors to the WRNi using xenograft tumor models in athymic nude mice." (PMID 34772932, 2021). "Across cancer types, only 89% of patients with a germline BRCA1 variant and 79% of patients with a BRCA2 variant have a tumor with complete loss of the wild-type allele." (PMID 34067105, 2021). "EEF1A1 mRNA expression was associated with increased sensitivity to olaparib in the GDSC pan-cancer cell lines and found to be highly expressed in olaparib-sensitive HGSOC cell lines, including BRCA2-mutated cell line OV4453, compared to resistant cell lines." (PMID 33803939, 2021). "Evidence for the role of specific genetic factors conferring risk for these cancers culminated with the discoveries of BRCA1 and BRCA2, the BC and OC cancer predisposing genes." (PMID 34298626, 2021). "The results revealed considerable differences in BRCA1- and BRCA2-dependent transcriptome landscapes in the studied cancers." (PMID 33525353, 2021). "SYCP3 is a meiosis‐specific gene, but also expressed in several cancer types, in which it impairs mitotic recombination by interfering with BRCA2, sensitizing certain tumor cells to PARPis; hence, we wanted to investigate this in TGCTs as well." (PMID 33513287, 2021). "While PARPi are generally inefficient against HR-proficient tumors, it was shown that inhibiting the HR pathway with RAD51 shRNA or with small-molecule inhibitors disrupting the RAD51/BRCA2 interface sensitized cancer cells to PARPi." (PMID 34208492, 2021). "MBC patients who were carries of P/LPVs in BRCA1 or BRCA2 were more likely to report a family history of other HBOC-related cancers in first- and/or second-degree relatives (70% vs. 29.5%, p = 0.001)." (PMID 33891299, 2021). "Specific cancer-associated mutations in the OB-folds of BRCA2 disrupt the interaction with PAR and stop the recruitment of BRCA2 to DNA lesions, strongly implicating the role of OB-folds in DNA repair and cancer etiology." (PMID 34283091, 2021). "Comprehensive cancer panel testing revealed pathogenic variants in cancer genes other than BRCA1 and BRCA2, suggesting that testing only BRCA1 and BRCA2 would have missed 8 out of 44 suspected HBOC patients (18%)." (PMID 33558524, 2021). "The age at diagnosis of cancers other than breast and prostate was 65 years in BRCA2 carriers versus 67 years in BRCA1 carriers." (PMID 34575694, 2021). "A comprehensive genetic panel, including germline mutations of BRCA1, BRCA2, MMR genes, and other cancer susceptible genes based on family history, should be used to determine appropriate therapy and clinical trial eligibility." (PMID 33947030, 2021). "We conducted a similar multivariate regression analysis for somatic mutations, and identified 24 significant associations in five (i.e., BRCA1, BRCA2, ATM, ATR, CHEK2) genes and higher HRD (FDR < 0.05) across cancer types." (PMID 34572800, 2021). "As shown, BC is the most frequent cancer, confirming that the BC risk in BRCA1 and BRCA2 mutation carriers is 45–80%." (PMID 33484353, 2021). "Here, we show that BRCA2 is required for homologous recombination in a normal developing tissue long before cancer arises." (PMID 34359565, 2021). "For the combined likelihood ratio (LR), we compared personal/family cancer history between the pathogenic (349 cases in BRCA1+, 291 cases in BRCA2+) and benign (2931 cases) groups." (PMID 34063308, 2021).
cancer (continued). "If pathogenic or likely pathogenic alterations in BRCA1, BRCA2, ATM, PALB2, and CHEK2 are found, and/or there is a strong family history of cancer, then patients should be referred for genetic counselling and confirmatory germline testing." (PMID 33630412, 2021). "Within the genes BRCA1 or BRCA2, cancer cluster regions are genetic regions containing a disproportion amount of gene mutations." (PMID 34711195, 2021). "So far, known genetic determinants of HPC are deleterious mutations in pan-cancer DNA repair genes (e.g., BRCA1, BRCA2, ATM, etc.)or in the PCa-specific risk genes, HOXB13." (PMID 33947030, 2021). "Breast cancer 2 (BRCA2) has been shown previously to interact with RAD51 and mediates RAD51-dependent DNA repair." (PMID 34819065, 2021). "Loss of BRCA2 function sensitizes cells to PARP inhibitors, which have been clinically exploited to treat an increasing number of cancers that harbor such mutations." (PMID 34283091, 2021). "It is difficult to make a direct comparison between BRCA2-mutated and BRCA1-mutated tumors as the distribution of these mutations differs across cancer types and the correlation between the BRCA1 mutation status and OS was not controlled for tumor type." (PMID 34067105, 2021). "The global association of BRCA1/2 mutations with diverse forms of cancer is likely due to the crucial function of both BRCA1 and BRCA2 in DNA repair systems, which are cornerstone to physiological functionality and maintenance of cells throughout the body." (PMID 34070674, 2021). "Although the ABCD test cannot explain the BRCA status of non-BRCA1/2 tumors, it is a rapid and precise method that directly evaluates the PARP inhibitor sensitivity of cancers harboring BRCA2 VUSs." (PMID 32444794, 2020). "Germline variants in BARD1 and CHEK2 have indeed been shown to be enriched in NB patients, while BRCA2 has been shown to be enriched in pediatric cancer patients." (PMID 33384420, 2020). "There are important uncertainties and differences in strength of evidence and differential effects for BRCA1 and BRCA2 with regard to these and other possible additional cancer risks." (PMID 32655641, 2020). "Many studies suggest that the status of the DDR pathway affects cancer cells’ response to chemotherapy, with loss of DDR elements increasing the sensitivity to DNA-damaging platinum and PARP inhibition, such as BRCA1, BRCA2, BARD1, ATM, and PALB227." (PMID 32457312, 2020). "Current guidelines recommend BRCA1 and BRCA2 genetic testing for individuals with a personal or family history of certain cancers." (PMID 32376921, 2020). "Studies on the cancer risk of fertility treatment in women with mutations in the genes BRCA1 and BRCA2 are sparse." (PMID 32719921, 2020). "PARPi were particularly effective in the treatment of patients with breast, ovarian, or other cancers, who were BRCA1 and/or BRCA2 deficient." (PMID 32300589, 2020). "The second most frequent PV, found in 12 families and involving a total of 49 subjects (10.1%), including 20 cancer patients (12 probands and 8 family members), is named BRCA2-1466delT (HGVS nomenclature: c.1238del; p.Leu413fs)." (PMID 32380732, 2020). "Of the cancer predisposition genes identified to date, BRCA1 and BRCA2 have been determined to be associated with hereditary breast and ovarian cancer syndrome." (PMID 32269964, 2020). "Here, we develop a genome-wide mutational scar-based pan-cancer Classifier of HOmologous Recombination Deficiency (CHORD) that can discriminate BRCA1- and BRCA2-subtypes." (PMID 33149131, 2020).